HMGA1 (high mobility group AT-hook 1)
Diseases named in the same sentence as HMGA1 in open-access papers (continued):
Sharing a sentence is not in itself a finding about the gene and the disease.
non-small cell lung carcinoma (18 papers, 2013 to 2024). A group of at least three distinct histological types of lung cancer, including non-small cell squamous cell carcinoma, adenocarcinoma, and large cell carcinoma. "Similar results were obtained in H1299, a human non-small cell lung cancer (NSCLC) cell line that express endogenous HMGA1." (PMID 39134516, 2024). "The HMGA1 gene also belonged to a panel of selected transcription factor genes, the expression of which allowed for the differentiation of small cell and non-small cell carcinoma." (PMID 35948739, 2022). "HMGA1 is enriched in several aggressive cancer types, including non-small cell lung cancer (NSCLC), where both mRNA and protein expression are substantially increased." (PMID 33505435, 2020). "We have recently demonstrated that aberrant PI3K signalling in Non-Small Cell Lung Cancer cells induces the mRNA expression of oncogenic transcription factors (HMGA1, JUN-B, FOS and MYC)." (PMID 23408974, 2013). "Moreover, LINC01748 regulates the miRNA-520a-5p/HMGA1 axis to exert carcinogenic effects in non-small cell lung cancer." (PMID 36212130, 2022). "Thus, we explored the HMGA1 mRNA expression data from Oncomine related to small cell lung cancer, the main three subtypes of non-small cell lung cancer, and lung carcinoids." (PMID 35805937, 2022). "Blood HMGA1 mRNA level could be a promising factor in the prognostication of non-small cell lung cancer patients." (PMID 35948739, 2022). "We hypothesized that IL-24 inhibits AKT by regulating the HMGA1/miR-222 axis in non-small cell lung cancer (NSCLC)." (PMID 27602961, 2016). "HMGA1 and HMGA2 are overexpressed in pancreatic adenocarcinomas and non-small cell lung carcinomas (NSCLC), in both squamous and adenocarcinoma histotypes." (PMID 31614829, 2019). "Albeit in a different cellular model, i.e., in non-small-cell lung cancer (NSCLC) cells A549, it is intriguing that both HMGA1 and YB-1 have been demonstrated to bind to the promoter of cyclin D1 and to be responsible for its transcriptional regulation." (PMID 31382504, 2019). "HMGA1 and HMGA2 proteins were overexpressed in non-small cell lung carcinomas (NSCLC), in both squamous and adenocarcinoma histotypes, in comparison with normal lung and benign tissues." (PMID 25859543, 2015).
triple-negative breast carcinoma (18 papers, 2013 to 2025). An invasive breast carcinoma which is negative for expression of estrogen receptor (ER), progesterone receptor (PR), and human epidermal growth factor receptor 2 (HER2). "In invasive triple-negative breast cancer cells, mutating the three HMGA1 serines (99, 102, and 103) phosphorylated by casein kinase 2 (CK2) results in decreased HMGA1 secretion and disrupts the invasive properties of the cell line." (PMID 35805937, 2022). "HMGA1 is secreted in invasive triple-negative breast cancer (TNBC) cells via unconventional protein secretion (UPS) orchestrated by Casein kinase 2 (CK2), bypassing the classical endoplasmic reticulum (ER)-Golgi secretory pathway." (PMID 41145488, 2025). "GOBO tool showed that HMGA1 expression was significantly higher in basal-like and triple-negative breast cancer subtypes compared with luminal and HER2-positive tumors (p < 0.001)." (PMID 41463532, 2025). "One study suggests that HMGA1 establishes an autocrine loop in invasive triple-negative breast cancer (TNBC) cells, which mediates the migration, invasion, and metastasis of TNBC cells and predicts the onset of metastasis in these patients." (PMID 39040191, 2024). "HMGA1 establishes an autocrine loop in invasive triple-negative breast cancer (TNBC) cells, which mediates the migration, invasion, and metastasis of TNBC cells and predicts the onset of metastasis in these patients." (PMID 39040191, 2024). "High Mobility Group A1 (HMGA1) is an architectural chromatin factor involved in the regulation of gene expression and a master regulator in Triple Negative Breast Cancer (TNBC)." (PMID 35504904, 2022). "We confirmed the modulation of H3S10ph using a different HMGA1–targeting siRNA, different triple-negative breast cancer (TNBC) cellular models (MDA-MB-157 and MDA-MB-468 cells), and a different α–H3S10ph antibody." (PMID 31382504, 2019). "We have recently described that HMGA1 establishes an autocrine loop in invasive triple-negative breast cancer (TNBC) cells." (PMID 31779212, 2019). "It was found that TGF-β1 induced the expression of HMGA1 in both triple-positive breast cancer cells and triple-negative breast cancer cells." (PMID 25572132, 2015). "Prior studies using antisense or dominant-negative approaches in triple-negative breast cancer cells (MDA-MB-231 or Hs578T) also showed that anchorage-independent cell growth or colony formation are inhibited by HMGA1 repression." (PMID 23658826, 2013). "Here, we show for the first time that the high mobility group A1 (HMGA1) gene drives metastatic progression in triple negative breast cancer cells (MDA-MB-231, Hs578T) by reprogramming cancer cells to a stem-like state." (PMID 23658826, 2013). "Our studies presented here underscore the fundamental role for HMGA1 in tumor progression in preclinical models for aggressive, triple negative breast cancers." (PMID 23658826, 2013). "Here, we discovered that HMGA1 is a central factor in reprogramming poorly differentiated, triple-negative breast cancer cells." (PMID 23658826, 2013). "To define the role of HMGA1 in oncogenic properties and tumor progression, we silenced HMGA1 expression using lentiviral-mediated delivery of short hairpin RNA (shRNA) in cell lines derived from aggressive, triple negative breast cancers (MDA-MB-231, Hs578T)." (PMID 23658826, 2013). "We also discovered an HMGA1 signature in triple negative breast cancer cells that is highly enriched in embryonic stem cells." (PMID 23658826, 2013). "Next, we assessed the role of HMGA1 on tumorigenesis using in vivo models of triple negative breast cancer." (PMID 23658826, 2013). "In triple-negative breast cancer, HMGA1 overexpression can promote tumor invasion and metastasis." (PMID 35114891, 2022).
triple-negative breast carcinoma (continued). "However, the discovery of an extracellular HMGA1-RAGE autocrine loop in invasive triple-negative breast cancer (TNBC) cell lines implicates HMGA1 as a “moonlighting protein” with different functions depending upon cellular location." (PMID 34572547, 2021). "However, the laboratory of one of the authors (JV) recently uncovered exciting evidence implicating HMGA1 in extracellular oncogenic function in triple-negative breast cancer (TNBC) cell lines." (PMID 34572547, 2021). "Reinforcing this; the most significant (p=3.5×10-25) individual marker of cluster 0res0.75 is ITGB1 (CD29, a well-documented breast SCLC cell marker), and of cluster 3res0.75 is HMGA1 (p=1.8×10-15), a driver of the stem-like state in triple negative breast cancer cells (Figure 5Biii)." (PMID 29796188, 2018). "Recent study reports silencing HMGA1 could block proliferation, migration and invasion of triple negative breast cancer MDA-MB-231 cells." (PMID 27008379, 2016). "Indeed, a study from the Broad Institute at MIT identified HMGA1 as a key transcription factor enriched in triple negative breast cancer." (PMID 23658826, 2013). "In contrast, the triple-negative breast cancer (TNBC) cell lines MDA-MB-231 and BT549, which express high levels of both HMGA1 mRNA and protein, demonstrated significant resistance." (PMID 41463532, 2025). "HMGA1 is involved in reprogramming cancer cells to a stem-like status and in favoring metastatic progression in triple negative breast cancer cells (MDA-MB-231 and Hs578T); silencing HMGA1 inhibits stem cell properties within mammospheres and decreases invasive abilities of cells." (PMID 31963852, 2020). "Additionally, we examined the role of HMGA1, a non-histone chromatin-related protein that was recently described as a marker overexpressed in MYC-negative triple-negative breast cancer." (PMID 36433941, 2022).
lung adenocarcinoma (17 papers, 2013 to 2025). A carcinoma that arises from the lung and is characterized by the presence of malignant glandular epithelial cells. "Collectively, this study defines the immune microenvironmental remodelling associated with lymph node metastasis, establishes an effective risk prediction model (LNRScore), and highlights HMGA1 as a potential target for precision diagnosis and therapy in lung adenocarcinoma." (PMID 40988131, 2025). "An increase in HMGA1 mRNA level was associated with a proportional gain in the HMGA1 protein amount in both lung adenocarcinoma (R Spearman 0.40, p < 0.001; R Pearson 0.45 p < 0.001) and lung squamous cell carcinoma (R Spearman 0.61, p < 0.001; R Pearson 0.54, p < 0.001)." (PMID 35805937, 2022). "The results revealed that MYBL2, CENPA, FOXM1, E2F1, ZNF367, and HMGA1 are the most relevant upstream transcription factors in lung adenocarcinoma." (PMID 40885709, 2025). "To elucidate the role of HMGA1 in lung adenocarcinoma and pan‐cancer, we conducted multi‐dimensional analyses and functional experiments." (PMID 40988131, 2025). "This study seeks to explore the specific role of HMGA1 in prognostic value based on The Cancer Genome Atlas (TCGA) database of Lung adenocarcinoma (LUAD) and glycolysis progression in LUAD cells." (PMID 38706894, 2024). "Above all, the combination of extensive experimental screening in bioinformatics and data validation in basic experiments makes the mechanism of HMGA1 in lung adenocarcinoma more authentic and reliable, which is also one of the creative points of this article." (PMID 38706894, 2024). "Regarding the molecular mechanism of HMGA1 regulating glycolysis in lung adenocarcinoma, we added the related experiments of PI3K/AKT pathway." (PMID 38706894, 2024). "Regarding the molecular mechanism of HMGA1 regulating glycolysis in lung adenocarcinoma, we conducted the related experiments of PI3K/AKT pathway." (PMID 38706894, 2024). "This article innovatively provides detailed mechanism and correlated impacts of HMGA1 in lung adenocarcinoma by bioinformatics." (PMID 38706894, 2024). "We found that HMGA1 and FOXM1 were associated with poor prognosis for three cancers with high morbidity and mortality, namely lung adenocarcinoma (LUAD), liver hepatocellular carcinoma (LIHC) and pancreatic adenocarcinoma (PAAD)." (PMID 37240870, 2023). "It is the first time to confirm the mechanism of miR-512-5p/HMGA1 signaling pathway in lung adenocarcinoma." (PMID 36304135, 2022). "The protein expression of HMGA1 was increased in resistant tumor tissues compared with HMGA1 in sensitive lung adenocarcinoma tumor tissues." (PMID 36304135, 2022). "In our study, the HMGA1 expression level was consistently higher among men in both lung adenocarcinoma and lung squamous cell carcinoma." (PMID 35805937, 2022). "One of them was the HMGA1, which was significantly overexpressed in neoplastic tissue and the blood of both in lung squamous cell carcinoma and lung adenocarcinoma patients in the validation experiment." (PMID 35948739, 2022). "Acting as an oncogenic driver, circ-LIMK1 can regulate DDP resistance and tumor development in lung adenocarcinoma by targeting miR-512-5p/HMGA1 pathway." (PMID 36304135, 2022). "Collectively, circ-LIMK1 regulated DDP resistance in lung adenocarcinoma by targeting miR-512-5p/HMGA1 axis." (PMID 36304135, 2022). "Some studies have found that HMGA1 plays an important role in the study of lung adenocarcinoma-related processes, but the relationship between HMGA1 and miR-512-5p has not been reported." (PMID 36304135, 2022). "TCGA data provided by the UALCAN platform indicated that the HMGA1 promoter methylation level was significantly decreased in both lung adenocarcinoma and lung squamous cell carcinoma tissue in comparison with normal lung tissue." (PMID 35805937, 2022). "Expression levels of the GGPS1 and PMVK genes were only significantly correlated with HMGA1 expression in lung adenocarcinoma." (PMID 35805937, 2022).
lung adenocarcinoma (continued). "Knockdown of HMGA1 expression in human lung adenocarcinoma cell line reinforced gefitinib efficiency by reactivation of EGFR or PDGF downstream signaling." (PMID 35948739, 2022). "The chromatin architecture modification gene HMGA1 has recently been described to be aberrantly expressed in lung adenocarcinoma (LUAD)." (PMID 33505435, 2020). "In summary, HMGA1 expression is positively correlated with LNRScore and poor prognosis in lung adenocarcinoma, promotes tumour cell proliferation and migration, and is widely overexpressed in multiple cancer types, underscoring its potential as a universal oncogenic target." (PMID 40988131, 2025). "Significantly higher HMGA1 expression was also stated in both lung adenocarcinoma and squamous cell carcinoma compared to adjacent samples (p = 5.19 × 10−10 and p = 1.66 × 10−9, respectively) and unpaired samples (p = 3.59 × 10−96 and p = 1.36 × 10−152, respectively)." (PMID 35805937, 2022). "Of course, HMGA1 was also involved in the biological process of lung adenocarcinoma." (PMID 36304135, 2022). "In addition, the HMGA1 expression level was positively correlated with HMGA1 protein abundance in both lung adenocarcinoma and lung squamous cell carcinoma." (PMID 35805937, 2022). "Overexpression of HMGA1 could restore the inhibitory effects of miR-512-5p enrichment on lung adenocarcinoma cell malignant phenotypes." (PMID 36304135, 2022). "Finally, we show that AGT and HMGA1 mRNAs were upregulated while KLF6 mRNA was downregulated in human lung adenocarcinoma, as demonstrated by The Cancer Genome Atlas analysis." (PMID 33380422, 2021). "In a word, miR-512-5p could target HMGA1 in lung adenocarcinoma cells." (PMID 36304135, 2022). "The areas under the ROC curve (AUC) of the prognostic model showed that HMGA1 and FOXM1 had moderate discrimination performance in lung adenocarcinoma patients with 1- and 3-year OS (overall survival), and poor discrimination in 5-year OS." (PMID 37240870, 2023). "In our study, the targeting relationship between miR-512-5p and circ-LIMK1 or HMGA1 and their functions in the progression of lung adenocarcinoma were confirmed, which provided new ideas for overcoming DDP resistance in lung adenocarcinoma in the future." (PMID 36304135, 2022). "In summary, all the findings confirmed the relationships among circ-LIMK1, miR-512-5p, and HMGA1, as well as their functional mechanism in DDP-resistant lung adenocarcinoma." (PMID 36304135, 2022). "Previous studies have reported that some proteins including HMGA1, IDH1, CEA and CYFRA play a role in the development of lung adenocarcinoma." (PMID 33424830, 2020). "Previous reports have indicated that HMGA1 plays an important regulatory role in tumour stemness and metastasis, but its specific function in lung adenocarcinoma lymph node metastasis and immunosuppressive networks has not been fully elucidated." (PMID 40988131, 2025). "Borderline differences in CpG methylation of HMGA1 have been noted between smoking and never-smoking lung adenocarcinoma patients based on validation of clinical samples." (PMID 35805937, 2022). "Circ-LIMK1 could regulate the expression of HMGA1 by targeting miR-512-5p and thus regulate the related processes of DDP-resistant lung adenocarcinoma cells and promote sensitivity of DDP-resistant lung adenocarcinoma cells." (PMID 36304135, 2022). "A significant connection was observed between the HMGA1 expression level and overall survival times in lung adenocarcinoma (p = 4.7 × 10−8), but not in the lung squamous cell carcinoma subtype (p = 0.2403)." (PMID 35805937, 2022). "In both lung adenocarcinoma and squamous cell carcinoma, the level of HMGA1 expression was the lowest in non-smokers, of intermediate value in reformed smokers, and the highest in current smokers." (PMID 35805937, 2022).
lung adenocarcinoma (continued). "The high HMGA1 expression level was connected with shorter overall and first progression survival time among lung adenocarcinoma patients, but not lung squamous cell carcinoma patients." (PMID 35805937, 2022). "A connection was observed between HMGA1 expression level and nodal status in lung squamous cell carcinoma but not in lung adenocarcinoma, and the only significant difference in level was observed between N0 and N1 cases." (PMID 35805937, 2022). "Generally, the level of HMGA1 expression tends to be the lowest in non-smokers, of intermediate value in reformed smokers, and the highest in current smokers in both lung adenocarcinoma and squamous cell carcinoma." (PMID 35805937, 2022). "Our TMNplot analysis indicates that the HMGA1 expression level could discriminate with good sensitivity and specificity between cancerous and adjacent non-cancerous tissues in both lung adenocarcinoma and squamous cell carcinoma." (PMID 35805937, 2022). "In lung adenocarcinoma, nodal status was not connected with the expression level of the HMGA1." (PMID 35805937, 2022). "Our results suggest that overexpression of HMGA1, E2F6, IRF1, and TFDP1 and downregulation or no expression of SUV39H1, RBL1, and HNRPD in blood is suitable for diagnosis of lung adenocarcinoma and squamous cell carcinoma sub-types of NSCLC." (PMID 24564251, 2013).